BCL2 (BCL2 apoptosis regulator)
Diseases named in the same sentence as BCL2 in open-access papers (continued):
Sharing a sentence is not in itself a finding about the gene and the disease.
cancer (continued). "The ability of DMC and OSU to downregulate the expression of these anti-apoptotic proteins (e.g., Mcl-1, Bcl-2) may therefore represent an appealing strategy to re-sensitize cancer cells to chemotherapeutic agents." (PMID 34356673, 2021). "Thus, the overexpression of Bcl-2 or Bcl-xL totally prevents the apoptotic response induced by edelfosine in cancer cells, either from a hematological or solid tumor origin." (PMID 34065546, 2021). "Furthermore, copper oxide NPs (CuO-NPs) inhibited the proliferation of HT-29 and SW620 cancer cells by decreasing the expression of Bcl-2 and Bcl-xL." (PMID 33923200, 2021). "Developing additional Bcl-2 inhibitors with different affinity for other pro-survival BCL-2 members might also be useful in cancer with some genetic background." (PMID 33799470, 2021). "Consequently, genetic events that lead to Bcl-2 overexpression can promote both cancer and autoimmune responses." (PMID 34360795, 2021). "Many studies described the regulation of Bcl-2 by miR-148a in various cancer." (PMID 34722255, 2021). "Elevated expression of Bcl-2 protein has been found in several human cancers." (PMID 34638779, 2021). "Therefore, we suggest that the COL11A1/Akt/CREB axis inhibits cancer cell apoptosis by promoting BCL-2 and p-BAXSer184 expression and reducing BAX content." (PMID 33531986, 2021). "Elevated expression of Bcl-2 is involved in various cancer progression." (PMID 34638779, 2021). "Several studies were done to identify Bcl-2 inhibitors to be used for cancer therapy." (PMID 34181356, 2021). "Elevated expression of Bcl-2 is involved in many cancer progressions." (PMID 34638779, 2021). "In various cancers, TYK2 overexpression or GOF mutations lead to STAT1 or STAT3 activation and upregulation of anti-apoptotic proteins, including B-cell CLL/lymphoma-2 (BCL-2) and myeloid cell leukaemia-1 (MCL-1)." (PMID 34439323, 2021). "It has been reported that activated STAT3/Bcl-2 pathway could inhibit autophagy, further promoting the proliferation of cancer cells." (PMID 34611143, 2021). "Additionally, the modulation of Bcl-2 and Bax family proteins using compounds has broad implications in cancer therapy." (PMID 35153759, 2021). "Bcl-2 is one of the most important oncogenes in the field of apoptosis which can maintain mild a prooxidant state by enhancing mitochondrial respiration to sustain the survival of cancer cells." (PMID 34484567, 2021). "High expression of Bcl-2 mediates the resistance to cisplatin in various human cancers." (PMID 33810184, 2021). "In addition, the chemotherapy also augmented the levels of Bcl-2 protein, which is a classical inhibitor of apoptosis and represents a target for cancer therapy." (PMID 34959348, 2021).
cancer (continued). "A recent study finds that isorhamnetin is associated with anti-proliferation effects and cell apoptosis induction, and it could inhibit cancer cell growth and alters the expression of apoptosis-related genes involving Bcl-2, Bax, Caspase-3, and so on." (PMID 33506873, 2021). "The apoptosis-inducing effect of PA on these cancer cells is mainly observed as the elevation of Bax/Bcl-2 ratio, leading to the collapse of MMP, cytochrome C release, and activation of caspases-9, which in turn induces the activation of effector caspase-3 and -7." (PMID 33916780, 2021). "Over-expression of the Bcl-2 gene is involved in cancer development." (PMID 34638779, 2021). "Furthermore, additional driver mutations such as in MYC, BCL2, MMSET and FGFR3 are considered as important driver mutations in the development of cancer." (PMID 33572851, 2021). "In cancer cells with abnormally high levels of Bcl-2, photodamage by cross-linking or cleavage may limit the effectiveness of this important anti-apoptotic control." (PMID 34578640, 2021). "Furthermore, the expression of IAP family members, such as c-IAP1, c-IAP2, survivin, XIAP and livin, and Bcl-2 family members, such as Bcl-2, Mcl-1, Bak, and Bad, which play critical roles in cancer cells apoptosis regulation, was examined by western blotting." (PMID 34926237, 2021). "Furthermore, the ratio of BAX/BCL2, which is an index of apoptosis promotion, also differed dramatically between cancer and normal cells after thermal stimulation." (PMID 34728686, 2021). "MDA-7/IL-24 promotes cancer-selective apoptosis by inducing endoplasmic reticulum (ER) stress, which causes up-regulation of BiP/GRP78, induction of pro-apoptotic proteins (such as BAX), and repression of anti-apoptotic proteins (such as BCL-2)." (PMID 33670594, 2021). "Bcl-2 has been identified as being over-expressed in several cancers." (PMID 34638779, 2021). "In addition to cancer cell apoptosis, BCL2 was also reported to confer chemoresistance in colorectal cancer." (PMID 33469000, 2021). "In addition, other studies have also found that ursolic acid downregulated the expression of Bcl-2 by activating caspase-3, caspase-8, and caspase-9, thereby inhibiting the proliferation of cancer cells and inducing apoptosis." (PMID 34194533, 2021). "ABT-199, a selective inhibitor of BCL-2, shows remarkable efficacy in a large number of cancers." (PMID 34336680, 2021). "Our results matched with others who recently different extracts of Rhus spp. significantly inhibited the growth, proliferation, and viability of cancer cells by activating the apoptotic process via caspase-3 overexpression and the regulation of Bcl-2 anti-apoptotic protein." (PMID 33891003, 2021). "Therefore, researchers can use mRNA degradation strategies and small inhibitory molecules for targeted Bcl-2 therapy in a variety of cancers, such as breast cancer, colon cancer, and prostate cancer." (PMID 33796026, 2021). "BCL-2 was a famous oncogene that suppressed apoptosis in human cancer cells." (PMID 33623790, 2021). "Given the positive correlation between bcl-2 overexpression and tumorigenesis, compounds that downregulate bcl-2 may confer a therapeutic advantage in treating cancers." (PMID 33996900, 2021). "Bcl-2 signaling pathway plays important roles in human cancers." (PMID 34181356, 2021). "Bax is retrotranslocated from the mitochondria by Bcl2, Bcl-xl, and Mcl1 in resting cancer cells." (PMID 33589622, 2021). "Likewise, the overexpression of miR‐143 results in an increased level of Bax and a decreased level of Bcl‐2 level in HeLa cells, thus serving as the circumstantial evidence of anti‐cancer effects." (PMID 33417281, 2021). "They detected the highest value of the expression of anti-apoptosis genes Bcl-2 and livin in cancer cells compared with those co-cultured with T. spiralis E/S proteins and increased expression of pro-apoptosis genes Cyt-C, Apaf-1, caspase-9 and caspase-3 in the treated cancer cells." (PMID 33773560, 2021).
cancer (continued). "In addition, it can inhibit cancer growth and induce cell apoptosis by inhibiting the expression of Notch1, Notch2, Notch4, and Bcl-2." (PMID 34680441, 2021). "This strategy presented here will pave the way to acquire atomic-level information and shed fundamentally new light onto the molecular mechanism of native full-length human Bcl-2 protein, as well as open up the gateway for novel Bcl-2 selective cancer drug strategies." (PMID 33800399, 2021). "MiR-181b can be targeted in the human cancer cell lines BCL2 (to regulate multidrug resistance)." (PMID 34956174, 2021). "Thus, BCL2-targeted therapy has recently been introduced to cancer treatment with promising results." (PMID 34202143, 2021). "We first questioned whether cancer cells treated with C75 showed increased sensitivity to BH3 mimetic drugs such as the dirty/promiscuous antagonist of BCL-2, BCL-XL, and BCL-W navitoclax/ABT-263." (PMID 34675185, 2021). "Apoptosis in cancer cells depends upon the dynamic equilibrium of Bax and Bcl-2 expression." (PMID 34863080, 2021). "Thus, the low ratio of Bax to Bcl-2 is a crucial point in induction of cancer cell cycle progression, and the high expression of the ratio leads to potential cell apoptosis as well as results in the release of cytochrome c from mitochondria." (PMID 35069196, 2021). "However, data regarding the prevalence and the expression level of Bcl-2 in cancer cells are controversial." (PMID 34337053, 2021). "The balance of anti- (Bcl-2) and proapoptotic (Bax) genes can determine the fate of cancer cells." (PMID 34502426, 2021). "Bcl-2 plays a vital role in angiogenesis as well as cancer growth." (PMID 34638779, 2021). "As such, for substrates that are anti-apoptotic regulators, potential inhibition of cognate cathepsin proteases overexpressed during cancer development, can predictably have the effect of enhancing the levels of certain anti-apoptotic Bcl-2 sub-family members, and thus drive cancer progression." (PMID 33925117, 2021). "However, the induced overexpression of anti-apoptotic BCL-2 proteins in cancer cells can provide a new therapeutic strategy to inhibit cancer cell progression and metastasis." (PMID 34575429, 2021). "Using 19F NMR and a specific fragment library (Bionet) with fluorinated compounds we can successfully identify various binders and validate our strategy in the hunt for novel Bcl-2 selective cancer drug strategies to treat currently incurable Bcl-2 sensitive tumors." (PMID 33800399, 2021). "Hence, pharmacological inhibition of Bcl-2 indicates potency for the treatment of Bcl-2-dependent cancers." (PMID 34638779, 2021). "Furthermore, QC can stop the expression of antiapoptotic proteins such as Bcl-2 and terminate cancer metastasis." (PMID 34681170, 2021). "Therefore, another trend for the treatment of cancer is finding inhibitors targeting the Bcl-2 proteins." (PMID 34903979, 2021). "Consequently, the disruption in the Bcl-2/Baxratio, accompanied by reactive oxygen species (ROS) generation induced by TQ inside cancer cells, damages mitochondrial membrane potential, leading to the release of cytochrome c." (PMID 33540625, 2021).
cancer (continued). "Evidence of the impact of computational modeling in cancer therapeutics is the fact that our multiscale mathematical model of the VEGF-CXCL8-BCL-2 pathway suggested that metronomic dosing of a SMI of BCl-2 could provide optimal efficacy." (PMID 34984415, 2021). "Additionally, most anti-cancer treatments can induce apoptosis in cancer cells but CSCs in prostate and breast cancer exhibit enhanced expression of a potent anti-apoptotic molecule, B-cell lymphoma 2 (Bcl-2), thereby counteracting drug-induced apoptosis." (PMID 35006395, 2021). "HSF1 inhibition by using HSF1 shRNAs or KRIBB11 decreased the expression of HSF1 downstream proteins, such as HSP70 and HSP27, and also decreased the expression of HSP90/HSP70/BAG3 client proteins, such as BCL2, MCL1, EGFR, MET, and AXL, causing apoptosis of EGFR-TKI-resistant cancer cells." (PMID 34203709, 2021). "Additionally, B-cell lymphoma-2 (Bcl-2) family proteins are important regulators of apoptosis which are generally overexpressed in many cancer cells." (PMID 34903979, 2021). "The Bax and Bcl-2 ratio is very crucial for the induction of apoptosis in cancer cells, a high ratio of Bax:Bcl-2 regulates the mitochondrial pathway which further leads to activation of caspase-dependent apoptosis as well as the caspase-independent apoptotic pathway." (PMID 35069196, 2021). "STAT3 may upregulate Bcl-2 expression to inhibit autophagy, further promoting the proliferation of cancer cells." (PMID 34611143, 2021). "The cancer is known to be driven in part by increased expression of the pro-survival protein BCL-2." (PMID 34065859, 2021). "To test whether the BCL2 interactome was enriched for known cancer driver genes in G401 cells, and for genes involved in neurological disorders in GPiNs, we integrated genetic and proteomic data in Genoppi." (PMID 33972534, 2021). "This anti-apoptotic activity contributes to cancer development and also resistance to chemotherapy, as cancer cells often control the death mechanisms by elevating the expression of BCL-2, BCL-XL, and MCL-1, which neutralises the apoptotic action of the BH3-only proteins of the BCL-2 family." (PMID 34680203, 2021). "Dysfunctional or mutant Keap1 in cancer cells leads to an accumulation of Bcl2." (PMID 34400968, 2021). "In the G2/M phase of the cell cycle, it was observed by site-directed mutagenesis that several serine residues (in charge of drug-induced phosphorylation of Bcl-2) on Bcl-2 protein were translated and then induced to phosphorylation by Dol-10, which led to apoptosis of malignant tumor cells." (PMID 34202685, 2021). "As BCL-2 is a marker for tumorigenesis and neoplastic progression, it may be a potential marker for anti-cancer therapies." (PMID 35009072, 2021). "The use of Bcl2 inhibitor drugs is advocated in different cancers including leukemia." (PMID 33707419, 2021). "In addition, Bcl-2, which usually promotes cell survival and is considered an anti-apoptotic protein, was significantly reduced in treated cancer cells in favor of apoptotic markers, thus confirming BCP’s pro-apoptotic effect." (PMID 34830893, 2021). "This review discusses the role of Bcl-2 in cancer development; it could be exploited as a potential target for developing novel therapeutic strategies to combat various types of cancers." (PMID 34638779, 2021). "Therefore, the hyper-activation of Akt promotes cell survival via the stimulation of Bcl-2 and via the inhibition of Bax, which are in charge of cancer cell resistance." (PMID 34439105, 2021). "However, the inhibitory effect of monotherapy with cisPt and mAb as well as anti-MUC1 combined with PtPz4, PtPz6, and cisPt on Bcl-2 mRNA support rationality of applied therapy in anti-cancer treatment." (PMID 34206951, 2021). "Cancer cells can adapt to escape these cell death stimuli by modifying their intrinsic apoptosis machinery, either by upregulation of anti-apoptotic, or downregulation of pro-apoptotic, BCL-2 proteins." (PMID 35008216, 2021).
cancer (continued). "Therefore, we established the effect of VKNG-1 on the inhibition of the phosphorylated proteins, p-AKT and Bcl-2 in S1-M1-80 cancer cells using Western blotting." (PMID 34572902, 2021). "There are three approaches for targeting Bcl-2 in cancer therapy." (PMID 33535550, 2021). "Patient selections and development of biomarkers determinant of patient response might also be critical for improving the therapeutic outcomes of BCL-2 inhibitors in diverse types of cancer." (PMID 33799470, 2021). "Furthermore, it has been described that alpha-bisabolol can promote cytochrome C release from the mitochondria to the cytosol, caspase-3 activation, and reduction in the ratio of BCL-2/Bax, and pro-apoptotic pathways in several cancer cell lines." (PMID 34208088, 2021). "Furthermore, the antiapoptotic genes BCL2 and XIAP (X-linked inhibitor of apoptosis) are downregulated by natural products and upregulated in several cancer tissues." (PMID 34422220, 2021). "However, when comparing the BCL2 interaction partners in GPiNs versus a cancer cell line (G401), we found both a large set of shared interactors and interactors unique to each cell line." (PMID 33972534, 2021). "Moreover, CSNK2A1 renders cancer cells resistant to apoptotic stresses by activating BCL2 and suppressing PML, FOXO3, and PARP1." (PMID 34359939, 2021). "Moreover, STAT3 signaling pathway positively regulates CyclinD1, Survivin, Bcl-2, Bcl-XL, and Mcl-1 to facilitate cancer cell cycle progression." (PMID 34179090, 2021). "The bax/bcl-2 regulation is predominant mechanism of apoptosis evasion used by cancers." (PMID 34563048, 2021). "The inhibitors of Bcl-2 are efficient as single agents, and they might be extremely beneficial when combined with additional targeted agents which induce cell death in cancer cells." (PMID 34638779, 2021). "Our results demonstrated that the median mRNA expression of anti-apoptotic members (Bcl-2, Mcl-1, Bcl-xL) was lower in cancer than normal tissues, while the expression of pro-apoptotic members (Bid, Bim, Bax, Bak) prevailed in cancer tissues, compared to normal tissues." (PMID 35008345, 2021). "Notably, the pro-survival Bcl-2 proteins are frequently overexpressed in cancer cells dysregulating this balance in favor of survival and also rendering cells more resistant to therapeutic interventions." (PMID 33799470, 2021). "Venetoclax is a selective and potent BCL2 inhibitor that induces apoptosis in cancer cells." (PMID 34829820, 2021). "In addition, it has been reported that DNMT3a can regulate the expression of apoptosis-related genes in cancer cells through changing the methylation levels at the promoter regions of the apoptosis-related genes, such as Bad, Bax and Bcl2." (PMID 33634123, 2021). "Also, overexpression of miR-509-3p decreased expression of SOX2, CD44, and CD133, and enhanced expression of Bax and caspase-3 while repressed Bcl-2 expression in cancer cells." (PMID 34715859, 2021).